CD86 (CD86 molecule)
Diseases named in the same sentence as CD86 in open-access papers (continued):
Sharing a sentence is not in itself a finding about the gene and the disease.
tumor (continued). "The mechanism of action was that the vaccine promoted the expression of the surface molecules CD40, CD80, and CD86 of DCs, allowing DCs to efficiently present antigens to T cells, enhancing the proliferation and activation of CD4+ and CD8+ T cells in mice and delaying tumor growth." (PMID 37876967, 2023). "However, due to reduced levels of MHC class I and CD86 on antigen-presenting cells in S47 TBM, we interrogated whether the frequency of tumor-specific CD8+ T cells were significantly different between S47 and P47 TBM." (PMID 37441266, 2023). "The correlation analysis between the expression levels of CD86, CD206, and PD-L1 in cancer tissues of 60 patients with HCC and the clinicopathological features indicated the correlation of the expression of PD-L1 with the degree of tumor differentiation (χ2 = 7.855, P = 0.02)." (PMID 37306737, 2023). "Consistent with murine data, expression of HLA-DR, CD86, CD40 and PDL1 was significantly increased in CD141+ cDC1 DCs (equivalent to mouse XCR1+) and CD1c+ cDC2 DCs (equivalent to mouse CD11b+), but not in pDCs, both pre- and post-Flt3L, upon co-culture with NDV-preinfected tumor cells." (PMID 36418317, 2022). "viSNE analysis revealed that NDV-killed tumor cells preferentially induced activation of Lin-I-Ad+CD11c+ conventional DCs (cDCs), as indicated by upregulation of MHC II, co-stimulatory molecules (CD86, CD40) and PDL1, with similar effects in both cross-presenting XCR1+ cDC1 and CD11b+ cDC2 subsets." (PMID 36418317, 2022). "Activated M1 macrophages typically express CD40 and CD86 and secrete higher levels of proinflammatory factors than M2 macrophages, such as IL-1α, tumor necrosis factor (TNF), and IL-12, which mainly exert an antitumor immune response and directly kill tumor cells in the early stage of a tumor." (PMID 35740975, 2022). "Similar to treatment of mice with AZD5069/anti-PD1, we noted transfused immature neutrophils caused increased activation (CD86+) of intratumoural XCR1+ cDC1 cells and elevated CD8+ T cells in tumours, unlike mice transfused with equal numbers of mature neutrophils." (PMID 35477863, 2022). "Tumor-derived exosomes could restrain DC maturation, down-regulate the expression of surface markers like CD80, CD86, and MHC-II, and up-regulate the expression of CD11b and PD-L1, which ultimately obstructed the anti-tumor activity of Teff and reinforced immune evasion." (PMID 36335094, 2022). "In addition, CD86 protein expression remarkably negatively correlated with tumour differentiation and tumour node metastasis (TNM) stage, while CD163 protein expression significantly positively correlated with tumour differentiation and tumour size." (PMID 34964155, 2022). "According to the Pearson’s correlation analysis, the tumor DLK2 level was negatively correlated with the expressions of M1 macrophage markers such as HLA class II histocompatibility antigen, DR α chain (HLA-DRA) (* p = 0.0278), CD11c (integrin α X, ITGAX) (p = 0.0557), and CD86 (p = 0.0783)." (PMID 35456435, 2022). "Therefore, the HION@Macs could significantly increase M1‐related CD86, TNF‐α, and iNOS markers and decrease M2‐related CD206 marker, as well as, potent dendritic cells (DCs) maturation and tumor infiltration of CD8+ T cells." (PMID 37323705, 2022). "Similarly, the number of infiltrating CD86+ cells, which is a biomarker for DCs, was dramatically reduced in the mouse group KLN205OV−L1−FGGY, consistent with the results of cell type analysis in human tumor tissues by IO360." (PMID 35842613, 2022). "The specific markers that we analyzed include tumor stem cell markers (CD24, CD44), markers of immunosuppression (CD47, PD-L1), markers of cell adhesion (CD49d, ICAM-1), markers of lymphocytes co-stimulation (CD80, CD86), and markers of antigen presentation (MHC class I, MHC class II)." (PMID 34411144, 2021).
tumor (continued). "For example, cancer cells and tumor-antigen presenting cells are shown to express high levels of coinhibitory receptor ligands (PD-L1, PD-L2 and many other) with relatively low levels of costimulatory receptor ligands (CD80 and CD86) in the tumor microenvironment to promote T cell anergy." (PMID 33717081, 2021). "Moreover, we found that POLE expression in cancers significantly correlated with an immunosuppressive tumor microenvironment, higher intratumoral heterogeneity, and expression of immune checkpoint genes PDCD1, CTLA4, and CD86, possibly mediated via the JAK/STAT and Notch signaling pathways." (PMID 34950188, 2021). "CTLA4-CD80/CD86 signal initiates T cells anergy or exhaustion, which reduces the activities of T cells, whereas blockade of the interaction between CTLA4 and its ligands reverses effector T cells exhaustion, thereby reinforcing anti-tumor activities of T cells." (PMID 33868277, 2021). "Furthermore, our data suggest that it is possible that CD80, CD86, and the CTLA-4-dependent tumor immune escape is involved in the development of tumor aggressiveness, a hypothesis that also merits further study." (PMID 34745002, 2021). "Moxibustion upregulated the infiltration of CD4+ T cells and Th1 cells in the tumor, and the combinatorial therapy increased the proportion of CD8+ cytotoxic T cells (CTLs), CD4+T cells, Th1, Th9 cells, and M1 macrophages, as well as the expression of Cd69, Ifng, and Cd86 mRNA." (PMID 33456484, 2020). "Furthermore, when stimulated by tumor antigens, γδ T cells will up-regulate the expression of antigen-presenting molecules HLA-DR, costimulatory and adhesion molecules (CD80, CD86, CD40) and scavenger receptor CD36, which allow γδ T cells to participate in the elimination of tumor cells." (PMID 32413966, 2020). "For tumor-resident DCs, we found no changes in CD86 at either time point." (PMID 32754281, 2020). "Gels incorporating Dox-iRGD with or without CpG roughly increased the number of activated (CD86+MHCII+) tumor-infiltrating CD11c+ DCs by 50% as compared to treatment with gels containing CpG alone or untreated tumors, although the total number of DCs remained unchanged." (PMID 33173046, 2020). "Ipilimumab binds to CTLA-4 on T-cells, which inhibits its ability to bind to CD80/CD86, allowing for the expansion of a repertoire of antigen-specific anti-tumor cytotoxic CD8+ T-cells and CD4+ T-cells, which corresponds to an improved anti-tumor immune response." (PMID 33256089, 2020). "In addition, compared to non‐tumor tissue infiltrating DCs, all tumor‐infiltrating DC subsets exhibited an increased CD80 expression together with an upregulation of CD40 for pDCs and cDC1s, while the level of CD86 was found to be downregulated on tumor‐infiltrating pDCs." (PMID 33282290, 2020). "Furthermore, immature dendritic cells (iDC) responded to mCD40L with enhanced maturation and activation over sCD40L evidenced by higher expression levels of CD83, CD86, HLA-DR and CD54, increased secretion of IL12 and IL10 and higher tumour-antigen (TA) uptake capacity." (PMID 31941968, 2020). "The enhanced anti-tumor response with agents blocking the SIRPα-CD47 interaction may arise from the activation of multiple DC subsets (i.e. shown by increased CD86 expression) that is seen within the spleen (data not shown)." (PMID 31801627, 2019). "The absence of upregulation of MHC class I and II, CD80 and CD86 expression on the tumour cells following cisplatin supports the notion that cisplatin does not exert its immune effect by modulation of MHC or co-stimulatory molecules on the tumour cells." (PMID 30948731, 2019). "In similar fashion within the confines of the tumour, CTLA-4 fosters immunosuppression through the induction and differentiation of Treg cells along with the upregulation of IL-10 and IDO (indoleamine-2,3-dioxygenase) by means of a CD80 and CD86 counter signaling approach." (PMID 30893948, 2019).
tumor (continued). "Additionally, we observed a significantly higher expression of activation molecules, namely, HLA-ABC, HLA-DR, CD86 and CD40, in TIL-Bs derived from tumor samples with high levels of B cells in comparison to TIL-Bs derived from Blo (< 5% of total cells) samples." (PMID 31623665, 2019). "Since our results indicate that H-1299 tumor cells downregulate the expression of CD40, CD80, CD86, and HLA-DR on CD1c+ DCs isolated from healthy donors, we proposed that H-1299 cells may also block the expression of costimulatory molecules on CD1c+ DCs derived from NSCLC patients." (PMID 31921114, 2019). "Furthermore, we found that the expression of PD-L2, CD80, CD86, and CTLA-4 are also elevated in cytomegalovirus and EBV-positive tumor patients, suggesting anti-PD-L2 and anti-CTLA4 immunotherapy may be effective in patients with these types of tumors." (PMID 30911684, 2019). "Thus, consistent with the Raji in vitro studies above, T cells engineered with AbTCR reduce cytokine release without a loss of anti-tumor activity, in a PDX tumor model that lacks CD80 and CD86 costimulation." (PMID 30479831, 2018). "Additionally, the tumor specific DCs activate Th cells through the interactions between TCRs and MHC class II-antigen complexes as well as the binding between their costimulatory molecules, such as the binding between CD80/CD86 and CD28." (PMID 30740111, 2018). "Similarly, the co-stimulatory antigens CD80 and CD86 showed upregulation by incubation of DCs with tumor cells treated with EnAd but not cells treated with Ad5." (PMID 28345021, 2017). "In addition, CTLA-4 expression on tumor specific Tregs could contribute to tumor immune escape by increasing the suppressive anti-tumor immunity and by downregulating CD80/CD86 on antigen presenting cells." (PMID 28073373, 2017). "Furthermore, we show reduced expression of T cell co-stimulatory molecules, such as CD80 and CD86, in GBC-PC, supporting an immunosuppressive phenotype that might prevent tumor clearance." (PMID 28978142, 2017). "SUP3 was shown to enhance cross-presentation by CD8+ cDCs in vitro, up-regulate the expression of CD40 and CD86 co-stimulatory molecules and induce production of IL-6 and TNFα in DC, culminating in an antigen-specific CD8+ T cell response and increased immunization against tumor challenge." (PMID 29050360, 2017). "In addition, an up-regulation of macrophage receptors involved in cell activation and recruitment (e.g. CD80, CD86, CSF3R, CSF2RB and CD209) was observed 8 hours after treatment possibly indicating an increased presence of activated macrophages in the tumor at this point in time." (PMID 27463372, 2016). "After confirming that HIFU can enhance anti-tumor immunity, we focused on differential expression of miRNAs in tumors after HIFU treatment and searched the target genes of these miRNAs with a bioinformatics approach and a signal cascade consists of HIFU, miR-134 and CD86 was identified." (PMID 26485753, 2015). "Furthermore, the expression of all well-established costimulatory molecules, including CD40, CD54, CD80, CD83, CD86, 4-1BB, GITR (glucocorticoid-induced TNFR-related protein), OX40L, and SLAM (signaling lymphocytic activation molecule), was downregulated in DC-tumor fusion cells." (PMID 26605345, 2015). "CD86+ mature CD8α+ non-plasmacytoid DCs were unchanged in absolute number but their proportion in the spleen was modestly, yet significantly decreased at both ST and TT following tumor inoculation." (PMID 24575090, 2014). "EGFR inhibition did not change the expression of CD80, CD86, or PD-L1 on the tumor cells." (PMID 25240937, 2014). "Interestingly, we also found that NC+IL6 macrophages expressed high levels of CD86 and exhibited no obvious tumor-promoting M2 phenotype function." (PMID 25313135, 2014).
tumor (continued). "In this work we showed that in vitro VSSP treatment of both tumor-induced MDSCs and BM-MDSCs was sufficient to increase not only CD11c marker, typically associated with DCs, but also the co-stimulatory molecules CD40 and CD86." (PMID 24829762, 2014). "The results of our studies are entirely consistent with the concept that CD80- and CD86-expressing APC play a central role in mediating the immune protection induced by semi-allogeneic vaccines by activating a Th-1 response and instructing T cells responsible for killing autologous tumor cells." (PMID 17686178, 2007). "The CD86 IgV domain of BIg5 did not play a major role in the observed antitumoral immune response suggesting NK-cell mediated ADCC as the initial effector mechanism followed by activation of tumor specific T cells." (PMID 15242515, 2004). "Thus, a relative increase in CD86 may be related to an anti-TME: the distinct ratios of CD80 and CD86 in CCH and HS suggest an involvement of these molecules in the behavior of the investigated neoplasia." (PMID 40271486, 2025). "Moreover, miR‐210‐3p inhibitor‐treated tumor spheroids notably promote monocyte phenotypic skewing towards M1 polarized macrophages compared to control inhibitor transfected spheroids, as evident from the increased expression of CD80, CD86, iNOS and decreased expression of CD206 and CD163." (PMID 35658112, 2024). "In addition, we identified a new tumor‐associated macrophage subset named TAM‐C2, marked without CD86 expression (an important co‐stimulatory molecule for CD8+T cell activation), almost exclusively in patients with PCa, which is partly responsible for disease progression." (PMID 38483933, 2024). "Correlations between the upregulation of CD80, CD86, and CD28 have been found in OSCC, and the lack of change in CD28 and PD-1 transcripts in our tumor samples, which might have been associated with the complexity in CTLA4 abundancy, requires further stratification." (PMID 36983005, 2023). "In addition, a powerful and specific anti-tumor immune response was detected following vaccination due to DC maturation and T cell activation because incubated BDMCs with the cMn-MOF@CM-treated group upon ultrasound irradiation exhibited robust CD80, CD86 and MHCII expression." (PMID 36010836, 2022). "Due to their competition for binding to the ligands CD80 and CD86 and their antagonistic function in the control of the immune system, one could claim that the ratio of expression levels between CTLA-4 and CD28 in the tumor shifts towards CTLA-4, which would result in a higher CTLA-4/CD28 quotient." (PMID 35406584, 2022). "In addition, the rates of matured DCs (CD11c+CD86+CD80+) and cytotoxic T cells (CD3+CD8+) in lymph nodes after DiD@HMV treatment were also elevated, indicating that the HMVs could act as autologous tumor-cell vaccines for cancer immunotherapy." (PMID 36319625, 2022). "Furthermore, MHC class II and CD86 levels expression were elevated on DCs in the draining lymph nodes, and the CD8/Treg ratio was significantly increased in OC lesions, suggesting that heating of OC TIM has significantly increased tumor antigen presentation and promoted adaptive immunity in OC." (PMID 35869032, 2022). "Meanwhile, the percentage of CD11c+, CD40+, CD80+, and CD86+ DCs significantly increased in the mCALR group, while no significant change was observed in the percentage of MHCII+ DCs, suggesting that mCALR expression was closely associated with DC infiltration in tumor tissues." (PMID 34660305, 2021). "We further found that ITGA3 was negatively correlated with monocyte markers (CD86), TAM markers (CCL2 and IL10), and M2 macrophage markers (CD163 and MS4A4A), suggesting that ITGA3 could regulate the polarization of TAMs and promote tumor growth and metastasis." (PMID 34094951, 2021).
tumor (continued). "Human tumor cells and tumor-associated APCs often express high levels of PD-L1, PD-L2, ICOS-L, and B7-H3, which causes high co-inhibitory signals that are accompanied by a low CD28 co-stimulation of T cells, which is itself caused by low to absent CD80 and/or CD86 signals." (PMID 34948104, 2021). "Additionally, IL-18 also induces the expression of CD80, CD86, HLA-DR and HLA-DQ on NK cells derived from cancer patients, suggesting that IL-18 conferred NK cells on an APC-like phenotype, which indicates increased recognition and responsiveness to tumour antigens." (PMID 32168834, 2020). "We have also analysed MHC class I, MHC class II, CD80 and CD86 expression in vivo by immunofluorescent staining of cryosections (data not shown) and we could not detect any difference between tumours treated with cisplatin and immunotherapy compared to untreated tumours." (PMID 30948731, 2019). "In addition to inducing Type 1 IFNs, co-stimulatory molecules (CD80, CD86, CD80) are also upregulated and targeting these pathways may assist in overcoming tumor-induced DC tolerance, particularly when designing therapies that manipulate the DC directly such as vaccines." (PMID 31921140, 2019). "To determine whether Kindlin-3 expression may reflect the amount of tumor infiltrating leukocytes (TILs) we analyzed the mRNA levels of different immune markers in the same series of tumors and found that triple negative and ERBB2 tumors presented the highest levels of CD45, CD86, CD28 and CD4." (PMID 30477537, 2018). "However, CD86 expression was not significantly increased in any of the tumor cell lines tested." (PMID 27671170, 2016). "The results showed no detectable expression of CD80, CD83, or CD86 on the surface of γδ T cells from PBMCs of normal donors (control), peripheral-derived γδ T cells, and γδ T cells directly isolated from tumor tissues (defined as tumor tissue-derived γδ T cells)." (PMID 24741609, 2014). "However, it has been reported that Treg from tumor-bearing mice may impair the expression of DC costimulatory molecules CD80, CD86, and CD40, suppress DC production of proinflammatory cytokines IL-12 and TNF-α, and inhibit their ability to induce T-cell activation in vitro." (PMID 22110524, 2011). "In addition, NK cell activation of DCs in anti-tumour immunity appears to depend upon tumour expression of NKG2D ligands, or expression of costimulatory molecules such as CD70, CD80 or CD86; EMT6 tumours are immunogenic respond well to PDT and may be more susceptible to immune-mediated control." (PMID 17505510, 2007). "We have shown that the killing phenotype relies on direct cell‐to‐cell interaction between the target tumor organoids and the immune cells and was observed despite the absence of CD80 and CD86 costimulatory molecules, which is in line with previous reports." (PMID 39535369, 2025). "This resulted in increased immune regulator molecules such as CTLA4, PDL1, Tim3, VISTA, LAG3, CD38, CD80, CD86, MHC Class II, and PD-L1 being presented on the surface of trogocytic tumor cells compared to non-trogocytic tumor cells." (PMID 40440354, 2025). "Consequently, SLAMF7 provides an alternative co-stimulatory pathway that may trade speed for functional breadth, an attribute that could be particularly advantageous in tumor or otherwise immunocompromised microenvironments where CD80/CD86 expression is absent or functionally impaired." (PMID 40909279, 2025). "This inhibition successfully increases T cell activation by allowing CD28 to interact with CD80/CD86 without interference from CTLA-4, resulting in a more robust anti-tumor immune response." (PMID 40739089, 2025). "Despite M2 macrophages’ similar tumor-promoting role, Rnaseh2c-cKO did not affect M1 (CD80, CD86) or M2 (CD163, ARG1) marker expression in mouse HCC-infiltrating macrophages." (PMID 41361104, 2025).